ENSG00000285218 (novel protein)
Gene: Protein-coding gene on chromosome 3 (170,418,868 to 170,860,380, forward strand). Ensembl gene ENSG00000285218.
Genetic constraint (gnomAD): Loss-of-function variants: 1 observed, 7.66 expected, observed/expected ratio (o/e) 0.13, 90% interval 0.045 to 0.62. That is too few expected variants to judge how well the gene tolerates losing a copy. Missense variants: 102 observed, 144.75 expected, observed/expected ratio (o/e) 0.7, 90% interval 0.6 to 0.83. Synonymous variants: 74 observed, 68.62 expected, observed/expected ratio (o/e) 1.08, 90% interval 0.89 to 1.31.